CD4 (CD4 molecule)
Diseases named in the same sentence as CD4 in open-access papers (continued):
Sharing a sentence is not in itself a finding about the gene and the disease.
Parkinson disease (continued). "dendritic.cells, T.follicular.helper.cells, CD56dim.natural.killer.cells and Monocyte in FRHGcluster A than in FRHGcluster B. While Parkinson’s disease FRHGcluster A had higher proportions of Activated.CD4.T.cells, Activated.CD8.T.cells, Immature." (PMID 38127902, 2023). "Previous MR studies on Alzheimer’s disease suggest potential causal associations with BIN1, CCL27, C3, CD33, CD4 T cells, GDF-15 and SVEP1, whereas MR studies on Parkinson’s disease suggest a potential causal association with GPNMB, IL-6 and MIP1b." (PMID 37118290, 2022). "For example, there are increased numbers of CD4+ IL17+ T helper cells (CD4 Th-17) in peripheral blood of patients with Parkinson’s disease and IL17 blockage rescues cell death." (PMID 33504364, 2021). "Overall, the findings in this study point to a potentially critical role of brain parenchymal CD4 T cells in Parkinson’s disease neurodegeneration." (PMID 33704423, 2021). "In this study, we show that T cells, and more specifically CD4 T cells, contribute to the CNS innate immune cell response and dopaminergic neuron death in an α-syn driven mouse model of Parkinson’s disease." (PMID 33704423, 2021). "They show that CD4 T cells help mediate α-synuclein-induced myeloid inflammation and neurodegeneration, thereby providing insights into the neuroimmunology of Parkinson’s disease." (PMID 33704423, 2021). "The literature demonstrated that the adoptive transfer of CD4+CD25+ Tregs yielded neuroprotective effects through the suppression of microglial responses to stimuli in an animal model of Parkinson’s disease." (PMID 32878186, 2020). "A paradigm shift has emerged in Parkinson’s disease (PD) highlighting the prominent role of CD4+ Tregs in pathogenesis and treatment." (PMID 31619964, 2019). "In this regard, DRD3 expressed in CD4+ T cells has been described to play a relevant role favouring the development of Parkinson’s disease in mice intoxicated with MPTP." (PMID 31810491, 2019). "We have studied the changes induced by vaccination with α-synuclein in the CD4 T cell pool and its impact on brain microglia to understand the immune mechanisms behind successful vaccination strategies in Parkinson’s disease animal models." (PMID 27055651, 2016). "D3R expressed on CD4+ T cells has also been reported to have an important role in the pathogenesis of 1-methyl-4-phenyl-1,2,3,6-tetrahydropyridine-induced Parkinson's disease." (PMID 26095429, 2015). "Parkinson’s patients exhibit decreased peripheral CD4 and elevated γ/δ T cells in their peripheral blood and cerebrospinal fluid (CSF)." (PMID 25346865, 2014). "The third result, lymphocyte mediated immunity, is supported by research that links neurodegeneration in a mouse model of Parkinson's with the presence of CD4+ lymphocytes in the brain." (PMID 22300537, 2012). "Increased effector/memory T cells (Tem), defined as CD45RO+ and FAS+ CD4+ T cells and decreased CD31+ and α4β7+ CD4+ T cells were associated with progressive Unified Parkinson’s Disease Rating Scale III scores." (PMID 23054369, 2012). "Finally, we investigated the correlation between immune cell ratios and CD4 and SEMA6A expression in Parkinson’s disease patients to identify biomarkers associated with immune cell ratios." (PMID 41329689, 2025). "A GO/KEGG analysis predicted that the related gene sets in IL-23/IL-1β-cultured MP CD4+ T cells had enrichment of the terms “Alzheimer’s disease,” “Parkinson’s disease,” and “Huntington’s disease”, which are neurological diseases, and enrichment of “cytokine signaling pathway”." (PMID 37121980, 2023). "dendritic.cells, T.follicular.helper.cells, CD56dim.natural.killer.cells, and Monocyte were higher in Parkinson’s disease FRHGcluster A than in FRHGcluster B. While Parkinson’s disease FRHGcluster A had higher proportions of Activated.CD4.T.cells, Activated.CD8.T.cells, Immature." (PMID 38127902, 2023).
Parkinson disease (continued). "Early treatment with CD28SA attenuated dopaminergic neurodegeneration in the SN of hαSyn Parkinson’s disease mice accompanied with reduced brain numbers of activated CD4+, CD8+ T cells and CD11b+ microglia observed at the late disease-stage 10 weeks after AAV injection." (PMID 36587195, 2022). "We have shown for the first time the mechanisms behind α-synuclein vaccination and, importantly, how we can modulate microglia’s phenotype by regulating the CD4 T cell pool, thus shedding invaluable light on the design of neuroimmunoregulatory therapies for Parkinson’s disease." (PMID 27055651, 2016). "This study was supported by a grant from Fondazione CARIPLO to Marco Cosentino (Project 2011-0504: Dopaminergic modulation of CD4+ T lymphocytes: relevance for neurodegeneration and neuroprotection in Parkinson’s disease - The dopaminergic neuro-immune connection)." (PMID 27652978, 2016). "Importantly, dopamine receptor D3 (DAR3) expressed in CD4+ T cells is fundamental for promoting destruction of dopaminergic neurons in the substantia nigra in a mouse model of Parkinson’s disease." (PMID 24711809, 2014). "Notably, these changes in CD4+ T cell phenotypes were correlated with severity of motor function as scored by the Unified Parkinson’s Disease Rating Scale, part III (UPDRS III)." (PMID 25671101, 2014). "Furthermore, CD4+ T cells that infiltrate in the substantia nigra during MPTP-induced Parkinson’s disease produced high levels of IFN-γ and TNF-α, two cytokines that act synergistically in microglia to promote the inflammatory M1-like phenotype." (PMID 24711809, 2014). "Importantly, therapeutic strategies targeting CD4+ T cell infiltration or MHC class II expression have shown efficacy in mitigating nigrostriatal dopaminergic neuronal damage in α-synuclein overexpression models of Parkinson’s disease." (PMID 40358168, 2025). "This hypothesis may partly be supported by study in a mouse model of Parkinson disease where peripheral administration of blocking antibodies against RANTES reduced the infiltration of CD4+ and CD8+ T cells into the substantia nigra and prevented the loss of dopaminergic neurons." (PMID 30737597, 2019). "Studies have shown that peripheral CD4 and CD8 T cells in patients with Parkinson’s produce Th1/Th2 cytokines in response to α-synuclein, suggesting a chronic memory T-cell response." (PMID 40507988, 2025). "In this study, we identified seven hub genes—PI3, TMSB15A, CLEC4M, CD4, SEMA6A, PLXND1, and AVP—that collectively drive Parkinson’s disease progression through synergistic mechanisms." (PMID 41329689, 2025). "Subsequently, we investigated the effects of NJ-1A and Nar on the infiltration of CD4+ T cells and CD8+ T cells in the brains of MPTP-induced chronic Parkinson’s disease model mice." (PMID 40358168, 2025). "Parkinson’s patients also displayed increased HLA-DR T cells and CD45RO memory T cells, with a simultaneous decrease in naïve CD4 T cells compared to healthy controls." (PMID 38846945, 2024). "In an alpha-synuclein (α-syn) model of Parkinson’s disease (PD), Schonhoff and colleagues have shown that central nervous system (CNS)-associated macrophages (CAMs), but not microglia, potentially orchestrate CD4+ T cell recruitment and mediate an α-syn-induced inflammatory makeup." (PMID 37365158, 2023). "With Parkinson's, for instance, RAB7L1 in CD4+ naïve T cells is positively correlated and KANSL1-AS1 is negatively correlated across all adaptive immune cell types." (PMID 37454237, 2023). "Furthermore, CD4+ T-cells were found to be inversely correlated with the Hoehn and Yahr Staging Scale, which is used to describe symptom progression in PD, while IgG was positively correlated with disease duration and the Unified Parkinson’s Disease Rating Scale (UPDRS) section III." (PMID 38020762, 2023).
Parkinson disease (continued). "This proposed TCR/α-syn/MHC binding is supported by CD4 and CD8 T cell-derived cytokine responses in Parkinson’s disease patient blood to α-syn and smaller peptides of the protein." (PMID 33704423, 2021). "Remarkably, new findings have now been published demonstrating that CD4 and CD8 T cells from patients with Parkinson’s disease recognize α-synuclein peptides displayed by both HLA-class II and class I molecules, respectively." (PMID 29163539, 2017). "We found that chronic IVIg treatment steadily decreases the CD4/CD8 cell ratio in 3xTg-AD mice, as previously reported in a mouse model of Parkinson’s disease." (PMID 24655894, 2014). "Notably, both CD4+ and CD8+ T cell populations have been identified in the striatum and substantia nigra of Parkinson’s disease patients and in animal models." (PMID 40358168, 2025). "Moreover, CD4 and CD8 T cells are found in substantia nigra dense bodies in Parkinson’s patients, exhibiting higher levels than in the normal group." (PMID 38846945, 2024). "To further elucidate the involvement of peripheral immune cells, we studied epigenome-wide DNA methylation in isolated populations of CD14+ monocytes, CD19+ B cells, CD4+ T cells, and CD8+ T cells from Parkinson’s disease patients and healthy control participants." (PMID 37903812, 2023). "MHC-II expressing microglia were discovered in the substantia nigra of a rat model of PD, along with CD4+ and CD8+ T cells, suggesting these microglia are in an environment where they are primed to present Parkinson's related antigens for T cell recognition, furthering disease pathogenesis." (PMID 35370907, 2022). "It is important to note that although this study mainly implicates a CD4 T cell role in Parkinson’s disease, the CD8 T cell compartment has been shown to be dysregulated in human Parkinson’s disease, as well as to contribute to other preclinical models of the disease." (PMID 33704423, 2021). "In 1-methyl-4-phenyl-1,2,3,6-tetrahydropyridine (MPTP)-induced Parkinson’s disease (PD) mouse model, EGCG could increase the ratio of CD3+CD4+ to CD3+CD8+ T lymphocytes and modulate peripheral immune response." (PMID 34203004, 2021). "CD8+ and CD4+ T cells, but not B cells, infiltrate the brain during Parkinson's disease (PD), based on evidence from post-mortem human tissue samples and the 1-methyl-4-phenyl-1,2,3,6-tetrahydropyridine (MPTP) mouse model of PD." (PMID 31572381, 2019). "Removal of CD4+ T lymphocytes, but not CD8+ lymphocytes, for example, was previously associated with reduced MPTP-induced neuronal cell loss in a mouse model of Parkinson’s disease." (PMID 26558367, 2015). "Interestingly, it has been shown that CD4+ T cells were found to be involved in neuroprotection during the pathology of neurodegenerative disorders of the central nervous system (CNS) such as Alzheimer’s (AD) and Parkinson disease (PD)." (PMID 22860054, 2012). "More recently, peripherally circulating CD4 and CD8 T cells derived from individuals with Parkinson’s disease have been shown to produce Th1/Th2 cytokines in response to α-synuclein, suggesting there may be a chronic memory T cell response present in Parkinson’s disease." (PMID 33704423, 2021). "We found that PD patients exhibited decreased naïve CD8+ T cells (CD3+ CD8+ CD45RA+ CD45RO−) and increased late-differentiated CD4+ T cells (CD3+ CD4+ CD28− CD27−), compared to HC, which were not affected by anti-parkinsonism medication administration." (PMID 35608657, 2022). "On the other hand, RAG1KO mice, which are resistant to MPTP-induced Parkinson’s disease, acquire the capacity to respond to MPTP-induced neurodegeneration when WT, but not DAR3KO, CD4+ T cells were transferred." (PMID 24711809, 2014). "Taken together, the data here support the hypothesis that CD4 T cells, and not CD8 T cells, are crucial in both the CNS myeloid response and the neurodegenerative processes that occur in the AAV2-SYN model of Parkinson’s disease." (PMID 33704423, 2021).
Cognitive impairment (83 papers, 2010 to 2025). Abnormal cognition is characterized by deficits in thinking, reasoning, or remembering. "As with developmental delay, markers of early severe disease such as class C illness or lowest nadir CD4 count were consistently associated with cognitive impairment." (PMID 39745769, 2025). "In a Spanish cohort, the authors attempted to create a diagnostic algorithm to screen for cognitive impairment based on nadir CD4 counts and current CD4 counts in experienced patients." (PMID 39861924, 2025). "Conversely, a higher percentage of CD4+ T cells was linked to an increased risk of cognitive impairment (OR, 2.79; 95% CI, 1.52 to 5.09; p = 0.001), particularly evident in patients in King’s clinical stage 3." (PMID 38882692, 2024). "We found that an increase in CD4+ T cells was associated with an elevated risk of cognitive impairment, especially in ALS patients with advanced stages." (PMID 38882692, 2024). "In that study, the authors found that a higher count of CD4+ T cells decreased the risk of cognitive impairment, which contrasts with our findings." (PMID 38882692, 2024). "In previous studies, nadir CD4+ T-cell counts have been associated with cerebral and cognitive deficits in perinatally HIV-infected children." (PMID 31142789, 2019). "CD4+ nadir has been considered to have an association with cognitive impairment in HIV-infected individuals by many authors." (PMID 27992497, 2016). "This indicates a substantial prevalence of underappreciated active neuronal injury in untreated patients with advanced systemic disease which likely contributes to the risk conferred by low CD4+ T-cell nadir on cognitive impairment even after treatment." (PMID 25541953, 2014). "HIV-1 subtype D infections, which are associated with a faster rate of progression and lymphocyte CD4 decline, cognitive deficit and higher mortality, have rarely been found in native Europeans." (PMID 22359615, 2012). "This technique visualized brain deficits by comparing two groups through the ratios of Jacobian determinant values and demonstrated that the deficits in HIV subjects were also associated with clinical measures—CD4 + lymphocyte depletion and cognitive impairment." (PMID 40458466, 2025). "Low CD4 counts can exacerbate neuroinflammation and reduce neurotrophic support, contributing to structural brain changes commonly linked to mood disturbances and cognitive impairment." (PMID 40282923, 2025). "CD4+ TEMRAs were associated with cognitive impairment on the MMSE." (PMID 38867294, 2024). "There are several potential trajectories of cognitive impairments associated with low CD4 nadir." (PMID 38856821, 2024). "Notably, a higher percentage of CD4+ T cells was found to increase the risk of cognitive impairment in ALS (OR, 2.79; 95% CI, 1.52 to 5.09; p = 0.001)." (PMID 38882692, 2024). "Furthermore, in ALS patients, the decreased levels of blood CD4-positive T lymphocytes have been associated with cognitive impairment, whereas the Tregs were found to be dysfunctional, with impaired immunosuppressive ability." (PMID 37369603, 2023). "Additionally, lowered number of CD4+ T lymphocyte seemed to be an independent risk factor of cognitive impairment in ALS patients." (PMID 33845794, 2021). "The model combining older age at testing, lower education level, and lower number of CD4+ T lymphocyte predicted a higher risk of cognitive impairment of ALS patients, with an area under the ROC curve value of 0.842 (95% CI 0.775–0.933, P < 0.001), a sensitivity of 90.6%, and a specificity of 67.3%." (PMID 33845794, 2021). "In cross sectional studies, nadir CD4 has been consistently associated with cognitive impairment." (PMID 27194435, 2016). "Consistent with this idea, nadir CD4+ count is a factor that predicts cognitive impairment in PLWH and modifies ART magnitude effects on cognitive outcomes." (PMID 39741198, 2025).
Cognitive impairment (continued). "Increased immune cell numbers and CD4+ T cell cytokine production corresponded with cognitive deficits in 3xTg and 5xFAD mice, an effect most pronounced in 3xTg female mice at early ages and in SPF conditions." (PMID 40738263, 2025). "For example, consider a patient with the following characteristics: cognitive impairment (15 points), CD4+ICOS+ of 30% (22.5 points), CD19+PD-L1+ of 80% (27.5 points), plasma sICOSL of 500 ng/mL (40 points), and CSF glucose of 8 mmol/L (40 points)." (PMID 40352922, 2025). "Moreover, meningeal immune response might be related to learning and memory; in the pyemia-related brain disease condition, the meningeal CD4+ T cell infiltration has a protective effect on cognition, while blocking such CD4+T cells would cause cognitive impairments." (PMID 38933499, 2024). "Autophagy-related gene (ATG) 5 regulates blood lipids, chronic inflammation, CD4+ T-cell differentiation, and neuronal death and is involved in post-stroke cognitive impairment." (PMID 38511768, 2024). "Our study findings relating NCR-expressing CD4 T cell subpopulations to these subdomains suggests that they directly or indirectly affect cognitive impairment." (PMID 38949728, 2024). "Interleukin-6 (IL-6), tumor necrosis factor-a (TNF-a), and C-reactive protein have been shown to be linked to cognitive impairment, and changes in peripheral CD4+, CD8+, CD3+, and CD4+/CD3+ levels have been documented." (PMID 38322584, 2024). "Prior research has shown that enhancing the quantity or function of CD4 Tregs can ameliorate AD pathology and cognitive impairment." (PMID 38500057, 2024). "Early-stage depletion of regulatory CD4+ T cells in AD mouse models has been shown to worsen cognitive deficits, while enhancing their numbers with treatments like IL-2 can improve cognitive function and reduce Aβ plaque load." (PMID 38658964, 2024). "Several studies have reported the relationship of CD4+ T cells and cytokines with cognitive impairment." (PMID 36386524, 2022). "The baseline CD4 cell count informs the likelihood that progressive cognitive impairment is due to HAD, which occurs at counts of < 200 cells per mm3 in untreated patients." (PMID 32664858, 2020). "Demographic and clinical data collected on number and type of medications plus supplements, possible medication related side-effects, comorbidity, frailty, cognitive impairment, current CD4 count and viral load." (PMID 29843635, 2018). "We also performed logistic regression analysis to assess which CD4+ T cell population contributes to cognitive impairment." (PMID 28751644, 2017). "We then examined associations of soluble biomarker levels with markers of systemic infection (plasma HIV-1 RNA viral load, CD4+ T-lymphocyte count) and with global and domain-specific cognitive impairment and HAND stage." (PMID 25776526, 2015). "Alternatively, low CD4 nadir may have a persistent, albeit stable, influence on the level of cognitive impairment." (PMID 38856821, 2024). "Besides, GABA+ levels in the NMOSD‐CI group were negatively correlated with the frequency of CD4+CXCR5+ T cells, suggesting the underlying coupling mechanism between immune responses and neurotransmitter metabolism in cognition impairment in NMOSD patients." (PMID 38383066, 2024). "The current cohort of PWH entered the CHARTER cohort between 2003 and 2007 and the participants were considered to be already at higher risk of cognitive impairment due to the ART initiation guidelines in place at that time, which were based on low CD4+ T cell counts." (PMID 38789639, 2024). "CD4 + immune cells likely play a prominent role promoting an anxious phenotype, without modifying mechanical hypersensitivity, depressive-like behavior or cognitive deficits." (PMID 36311856, 2022). "ALS patients with a reduced peripheral CD4+ T lymphocyte level may be more vulnerable to cognitive impairment apart from aging processes and lower educational level." (PMID 33845794, 2021).